ALDOA (aldolase, fructose-bisphosphate A)
Diseases named in the same sentence as ALDOA in open-access papers (continued):
Sharing a sentence is not in itself a finding about the gene and the disease.
cancer (continued). "In the clinical component, we also showed that the combination of ALDOA and TRAF4 or DUSP4 is positively correlated with poor overall survival in a xenograft model and cancer patients through immunohistochemical analyses." (PMID 32188842, 2020). "At least half of the top genes in both the correlating and anti-correlating categories are cancer-related, including oncogenes (RRAS and ALDOA), providing further insight into the observed inverse relationship between the two diseases." (PMID 28382934, 2017). "Four enzymes (TPI1, AKR1B10, ALDOA, and AKR1B1) out of 34 enzymes in this pathway are overexpressed in cancer." (PMID 25243088, 2014). "For instance, in Glycolysis/ Gluconeogenesis and Biosynthesis of amino acids pathways, lysine 131 (K131) site of PGK1, K322 and K13 sites of ALDOA, K215 and K194 sites of GAPDH, K89 site of ENO1, K678 site of PFKM were hyper-lactylated in cancer cells and tissues." (PMID 40849487, 2025). "Some studies show that the inhibition of ALDOA, using GalNAc-siRNA or small molecule inhibitors, effectively suppresses cancer metabolism in HCC and PCa, suggesting that targeting ALDOA may be a promising target for treating cancer." (PMID 40076506, 2025). "Our work uncovers a previously uncharacterized and unexpected molecular mechanism for ALDOA in human cancer, which strengthens our understanding of the essential nonmetabolic functions and novel molecular action of ALDOA in tumorigenesis." (PMID 37431681, 2023). "Notably, however, MUC1-C-dependent, MYC-independent signaling was identified for induction of other genes, such as PFKL, ALDOA, and ENO2, that are essential for driving glycolysis and are upregulated in cancer." (PMID 37915591, 2023). "Thus, inhibition of ALDOA activity is most deleterious to cells undergoing EMT, a process that provides cancer cell invasion, and can be used as a universal approach to anticancer therapy." (PMID 37449059, 2023). "Based on the relationship between FBP1 and ALDOA in patients and the related cellular distribution, we hypothesized that ALDOA and FBP1 coregulate specific and identical molecules to control cancer progression." (PMID 35404841, 2022). "ALDOA also has non-enzymatic functions in invasive potential, drug resistance, and stem cell function of cancer cells." (PMID 36077431, 2022). "We found that ALDOA mainly affected the OS in the pan-cancer rather than DFS (OS: HR = 1.3, logrank P = 7.5e−15; DFS: HR = 1.1, logrank P = 0.079)." (PMID 35804089, 2022). "Recently, ALDOA was found to have nonenzymatic roles in cancer metastasis, drug resistance, and cancer stemness activity by interacting with different proteins." (PMID 35404841, 2022). "Even though UM0112176 inhibits the metabolic function of ALDOA, its cytotoxic effect on cancer cells is related to the inhibition of the non-metabolic functions of this enzyme mainly by disturbing the interaction of ALDOA with F-actin." (PMID 35628385, 2022). "Therefore, uncovering the effectors between ALDOA and FBP1 will lead to novel therapeutic strategies for cancer patients." (PMID 35404841, 2022). "In summary, MSPA exhibits anti-cancer effects by simultaneously targeting ENO1, ALDOA, and FH." (PMID 34681284, 2021). "Hence, it is important to investigate the effects of PLK1, ATM and ALDOA on the DDR and the potential value of these proteins as targets in cancer therapy." (PMID 34565365, 2021). "However, significant enhancement of ALDOA, TPI1, and DNAJB1 in MD/PD/WD metastatic OSCC compared to WD OSCC suggests enhanced cancer cell proliferation, metabolic reprogramming and oncogenic stress in the former." (PMID 32922662, 2020). "ALDOA and RACGAP1 are tubulin binding proteins important for the microtubule filaments system, and are mainly responsible for metastasis and invasiveness in various carcinomas." (PMID 33379356, 2020). "ALDOA and ENO1 were both found to be involved in tumorigenesis in different cancer types." (PMID 31847435, 2019).
cancer (continued). "AA genes, especially the hub genes would help to elucidate the non-glycolytic related functions of ALDOA in cancer." (PMID 28191039, 2017). "Although some papers suggested that this was correlated to glycolysis, Ritterson and Tolan have shown that silencing ALDOA drastically decreased the rate of cancer cell proliferation, and this did not greatly interfere with cellular energy metabolism." (PMID 28191039, 2017). "Additionally, to compensate for the reduction in ATP production under hypoxic conditions, cancer cells can stimulate glucose uptake and metabolism by inducing GLUT3 and ALDOA." (PMID 27793029, 2016). "Two enzymes (ALDOA, PGD) from pentose phosphate pathway (27 genes) are overexpressed in cancer." (PMID 25243088, 2014). "This could also be a mechanistic explanation for the unique essentiality of ALDOA observed across hundreds of human cancer cell lines in the Cancer Dependency Map, a phenotype not shared by other glycolytic enzymes." (PMID 39833612, 2025). "Furthermore, the expression of ALDOA and FBP1 also showed similar trends in multiple cancer stages." (PMID 35404841, 2022). "Altered energy metabolism in cancer cells is accompanied by the upregulation of several glycolytic enzymes, such as GLUT1, hexokinase 2, phosphofructokinase, enolase 1 (ENO1), aldolase A (ALDOA), lactate dehydrogenase A, and pyruvate dehydrogenase kinase, which stimulate the Warburg effect." (PMID 34681284, 2021). "Interestingly, in this study, we demonstrated that ALDOA also has a novel nonenzymatic function in promoting cancer stemness." (PMID 32188842, 2020). "However, accumulated studies have proven that ALDOA also promotes cancer growth and metastasis through its non-enzymatic functions." (PMID 31384177, 2019). "Positive association between ALDOA and hub genes relevant to cell cycle remained even after minimizing the effect of glycolysis, indicating that ALDOA might contribute to cell proliferation of cancer, at least partially independent of glycolysis." (PMID 28191039, 2017). "Indeed, ALDOA was the only glycolytic enzyme that showed CE both in our RNAi screen in murine HCC cell lines with different oncogenotypes cultured under diverse environmental conditions and across the multiple cancer cell lines represented in the Cancer Dependency Map." (PMID 39833612, 2025). "To understand whether the relationship between ALDOA and FBP1 in patients was also reflected in cell lines, we conducted correlation analysis using the CCLE dataset, which is a complete analysis of the gene expression differences between multiple cancer cell lines." (PMID 35404841, 2022). "However, there is no clear report on the role of ALDOA in pan-cancer." (PMID 35804089, 2022). "Increased ALDOA and decreased FBP1 levels are phenotypic characteristics in human cancers without the molecular explanation of how ALDOA and FBP1 regulate the FBP utilization." (PMID 36077431, 2022).
infection (8 papers, 2011 to 2024). The state of being infected such as from the introduction of a foreign agent such as serum, vaccine, antigenic substance or organism. "Strikingly, infection with individual ALDOA sgRNAs led to a more acid-resistant phenotype in both SW480 and COLO320DM cells." (PMID 35263578, 2022). "In our mouse model, ALDOA was upregulated in the late infection stage and appeared at the PPI core." (PMID 39625960, 2024). "Finally, we analyzed the effect of infection on the cellular distribution of AldoA, EWSR1 and ILF3-90." (PMID 36306280, 2022). "It was shown that, upon EV-D68 infection, STING co-localised with PI4P as well as glycolytic enzymes, such as HK, PK, and ALDOA, as well as SLC2A1 (GLUT1) in ROs." (PMID 39459875, 2024).
adenocarcinoma (2 papers, 2021 to 2025). A common cancer characterized by the presence of malignant glandular cells. "To study the diagnostic value of ALDOA for distinguishing adenocarcinoma tissues from normal tissues, we performed ROC curve analysis with R package pROC." (PMID 34925439, 2021).
neurological disorders (2 papers, 2023). "We observed that the observed changes in ALDOA and ENO1 expression could induce various neurological disorders by modulating their direct interactors." (PMID 37664457, 2023).
bacterial infection (1 paper, 2022). "In summary, pathogenic bacterial infection upregulated PKM, LDHB, LDHA, ALDOA, PGD, GPI, and ALDOC, increased ATP production, which promotes leukocyte recruitment and NALP3-inflammasome activation, increases NADPH production, and promotes ROIs modulating inflammation and injury." (PMID 36335251, 2022).
neurodevelopmental disorder (1 paper, 2022). A behavioral and cognitive disorder with onset during the developmental period that involves impaired or aberrant development of intellectual, motor, or social functions. "The participants in our study with rare variants in ALDOA, KIF22, TAOK2 and SEZ6L2 did not present with ASD or neurodevelopmental disorders." (PMID 35330733, 2022).
ALDOA also shares sentences with these, for which no sentence is quoted: oral squamous cell carcinomas (5 papers); cervical adenocarcinoma (3); renal carcinoma (3); renal cell carcinoma (3); renal clear cell carcinoma (3); Alzheimer disease (2); esophageal cancer (2); head and neck squamous cell carcinoma (2); Intellectual disability (2); kidney cancer (2); meningitis (2); prostate adenocarcinoma (2); Acute hepatic porphyria (1); acute myeloid leukemia (1); alcohol abuse (1); brain cancer (1); brain disorder (1); cerebral infarction (1); cerebrovascular disease (1); cervical squamous cell carcinoma (1); cholangiocarcinoma (1); cognitive diseases (1); colon adenocarcinoma (1); colorectal (1); colorectal adenocarcinoma (1); colorectal adenoma (1); cyst (1); depression (1); dermatomyositis (1); developmental delay (1).
A further 39 diseases each share a sentence with ALDOA in 1 paper.